MIR221 (microRNA 221)
Synonyms: hsa-mir-221; MIRN221; miRNA221; mir-221
Gene: MicroRNA gene on chromosome X (45,746,157 to 45,746,266, reverse strand). Ensembl gene ENSG00000207870.
Gene Ontology:
Cellular component: RISC complex
Homologues: Orthologues: chimpanzee ptr-mir-221 (100% identical), macaque mml-mir-221 (100% identical), rat Mir221 (96% identical), mouse Mir221 (84% identical), guinea pig MIR221 (81% identical), tropical clawed frog xtr-mir-221 (66% identical), zebrafish dre-mir-221 (66% identical), pig ssc-mir-221 (62% identical), rabbit MIR221 (55% identical). Paralogues in human: MIR222 (45% identical).
Diseases named in the same sentence as MIR221 in open-access papers:
MIR221 is named in the same sentence as 13 diseases in open-access papers, as found by Europe PMC text mining. Sharing a sentence is not in itself a finding about the gene and the disease. The quoted sentences say what the papers report.
diabetes (2 papers, 2021 to 2025). "The transfer of Mir221 and Mir222 via vascular smooth muscle cells – derived exosomes from diabetes affected vascular inflammation." (PMID 39245438, 2025). "To further investigate the role of Mir221/222 in obesity and diabetes, we crossed male Tg (Adipoq-cre) mice and female Mir221tm2/y C57BL/6JJcl mice and generated male Mir221/222flox/y and male Mir221/222AdipoKO littermates." (PMID 35046889, 2021).
Obesity (2 papers, 2017 to 2021). Accumulation of substantial excess body fat. "The adipocyte-specific inhibition of Mir221/Mir222 expression protected the mice fed with HFHS chow from the obesity." (PMID 35046889, 2021). "Mir221 and Mir222 are paralogous genes and share the common seed sequence and Mir221/222AdipoKO mice fed with HFHS chow demonstrated resistance to the development of obesity compared with Mir221/222flox/y." (PMID 35046889, 2021). "Although miR-221-3p and miR-222-3p are differentially expressed in sera and adipose tissues, the functional in vivo experiments to elucidate the roles of Mir221 and Mir222 in obesity has not been reported." (PMID 35046889, 2021).
Arthritis (1 paper, 2024). Inflammation of a joint. "Our results establish an SF-specific pathogenic role of Mir221/222 in arthritis and suggest that its therapeutic targeting in specific subpopulations could lead to novel fibroblast-targeted therapies." (PMID 39235454, 2024). "To assess the therapeutic potential of Mir221/222 downregulation, we studied the impact of Mir221/222 deletion in arthritis." (PMID 39235454, 2024). "Notably, Mir221/222 overexpression in arthritis rendered both layers more hyperplastic in huTNFtg;TgCol6a1-Mir221/222 mice compared to huTNFtg." (PMID 39235454, 2024). "Interestingly, during Mir221/222 overexpression in arthritis, the expression of ECM-related molecules in SFs was found altered and, more specifically, Prg4 and the integrin component Itga3 were downregulated." (PMID 39235454, 2024). "Mesenchymal Mir221/222 overexpression leads to worse arthritis manifestations in huTNFtg mice." (PMID 39235454, 2024). "Deletion of Mir221/222 ameliorates arthritis in huTNFtg mice." (PMID 39235454, 2024). "To examine whether the effect of Mir221/222 on arthritis manifestations was SF-mediated and exclude a contributing indirect role of Mir221/222 sufficiency from other cell types, we generated huTNFtg;TgCol6a1-Mir221/222;Mir221/222-/- mice." (PMID 39235454, 2024). "Finally, transcription factor motif enrichment analysis revealed transcription factors such as Rela, Relb, Junb, Nfe2l2, and Bach1 that could regulate the expression of Mir221/222 in arthritis." (PMID 39235454, 2024). "Mir221/222 regulate cell cycle signaling and ECM-related pathways in arthritis." (PMID 39235454, 2024). "Additionally, Mir221/222 deletion in arthritis did not alter the inflammatory influx, but rather led to the inhibition of fibroblast expansion of LL and SL in the joints." (PMID 39235454, 2024).
breast carcinoma (1 paper, 2024). "MIR221 and MIR222 were identified as regulators of epithelial‐to‐mesenchymal transformation (EMT) in breast cancer, contributing to the progression and metastasis of cancer." (PMID 39210544, 2024).
glioblastoma (1 paper, 2025). The most malignant astrocytic tumor (WHO grade IV). "Elevated levels of Mir221 and Mir222 in glioblastoma promote cell survival, while reducing the levels of these miRNAs leads to increased apoptosis through the upregulation of BBC3/PUMA." (PMID 39245438, 2025).
Intellectual disability (1 paper, 2018). "It has been suggested that MIR222, with or without MIR221, is a plausible candidate to cause intellectual disability associated with X-linked retinal dystrophy in the Xp11.3 deletion syndrome." (PMID 30567555, 2018).
Sepsis (1 paper, 2024). Sepsis is defined as life-threatening organ dysfunction caused by a dysregulated host response to infection. "Additionally, Tnf has been reported to be a direct target of Mir221 and Mir222 in sepsis in macrophages." (PMID 39235454, 2024).
cancer (2 papers, 2021 to 2024). A tumor composed of atypical neoplastic, often pleomorphic cells that invade other tissues. "Mir221 and Mir222 demonstrated the angiogenic activities in vascular cells and cancers, however, we did not observe the angiogenesis activities in WATs in Mir221/222AdipoKO mice." (PMID 35046889, 2021).
cardiovascular diseases (1 paper, 2025). "Mir221 and Mir222 have been reported to be closely related to inflammation and the pathogenesis of cardiovascular diseases." (PMID 39245438, 2025).
MIR221 also shares sentences with these, for which no sentence is quoted: cardiac hypertrophy (1 paper); prostate (1); prostate carcinoma (1); vitiligo (1).